AR (androgen receptor)
Diseases named in the same sentence as AR in open-access papers (continued):
Sharing a sentence is not in itself a finding about the gene and the disease.
hypothyroidism (3 papers, 2021 to 2026). Abnormally low levels of thyroid hormone. "The question of how hypothyroidism diminishes growth of PCa could be possibly addressed in the future using more specific drugs with less side effects to block the thyroid hormone pathway, potentially in combination with AR blockers." (PMID 33034050, 2021).
Impaired glucose tolerance (3 papers, 2012 to 2025). An abnormal resistance to glucose, i.e., a reduction in the ability to maintain glucose levels in the blood stream within normal limits following oral or intravenous administration of glucose. "Progressive reduced insulin sensitivity and impaired glucose tolerance were observed in AR knockout mice with advancing age." (PMID 40274775, 2025).
Kallmann syndrome (3 papers, 2024 to 2025). Kallmann syndrome (KS) is a developmental genetic disorder characterized by the association of congenital hypogonadotropic hypogonadism (CHH) due to gonadotropin-releasing hormone (GnRH) deficiency, and anosmia or hyposmia (with hypoplasia or aplasia of the olfactory bulbs). "In addition, genetic testing for SRD5A2 and AR abnormalities was not conducted, and with the exception of one patient diagnosed with Kallmann syndrome, the primary cause remained undetermined." (PMID 40813749, 2025).
leiomyoma (3 papers, 2024 to 2025). A well-circumscribed benign smooth muscle neoplasm characterized by the presence of spindle cells with cigar-shaped nuclei, interlacing fascicles, and a whorled pattern. "In patient leiomyoma samples, we found a peak upstream of the AR gene which was significantly enriched in anti-PR ChIP compared to no immunoprecipitation controls." (PMID 39088439, 2024). "FKBP5, a co-chaperone in glucocorticoid and androgen receptor signaling, was reported highly expressed in fibroids and may regulate genes involved in proliferation and apoptosis in leiomyoma cells." (PMID 40474053, 2025). "This regulation occurs through the AR-cAMP-PKA-dependent signaling pathway, potentially impacting the occurrence and development of fibroids." (PMID 38890689, 2024).
medullary carcinoma (3 papers, 2020 to 2021). "Previous studies showed that AR activity in non-medullary thyroid carcinomas, as determined by ligand binding activity, was found to be higher in a majority of men and lower in a majority of women compared with normal thyroid tissue." (PMID 32365531, 2020). "In the medullary carcinoma case (BC8) and the metastatic case (BC9), an AR + PR double positive population appeared." (PMID 33266334, 2020).
metastasis (3 papers, 2017 to 2020). The spread or migration of cancer cells from one part of the body (where they first appeared) to another. "Another study analyzed the expression of the lncRNA, HOTAIR, in 163 cases of TNBC and found that its expression in tumor tissues is strongly correlated with lymph node metastasis and has a direct strong association with androgen receptor (AR) expression." (PMID 33330019, 2020).
metastatic melanoma (3 papers, 2021 to 2025). A melanoma that has spread from its primary site to another anatomic site. "Our findings consistently show that AR is more expressed in metastatic melanoma cells as compared with those obtained from primary lesions." (PMID 39837817, 2025). "AR expression was positively associated with EGFR in both primary and metastatic melanoma lesions from male as well as female patients." (PMID 37838724, 2023). "By interrogating the Genomic Data Commons (GDC) Cancer Genome Atlas (TGCA) SKCM for AR gene expression in primary and metastatic melanoma, we found that AR gene, analyzed by RNA-seq in a cohort of 481 patients, was more expressed in metastatic rather than primary tumor." (PMID 39837817, 2025). "Double immunofluorescence (IF) analysis of melanocytes in benign or dysplastic nevi or metastatic melanoma versus melanocytes from flanking skin showed consistently increased levels of AR expression in the melanocytic lesions, with heterogeneity of AR protein expression at the single-cell level." (PMID 33112375, 2021).
Nephropathy (3 papers, 2006 to 2023). A nonspecific term referring to disease or damage of the kidneys. "For example, kaempferol effectively impedes calcium oxalate crystal-mediated kidney damage and crystal deposition through the modulation of AR/NOX2 signaling." (PMID 36866869, 2023).
oral cancer (3 papers, 2022 to 2024). "This method directly assesses oral cancer biomarkers using the ELISA test to determine the levels of EGF, androgen (AR), and estrogen (ER) receptors." (PMID 37370896, 2023). "Our method directly examines the expression of oral cancer biomarkers, such as the epithelial growth factor receptor (EGFR), and steroid receptors, including the androgen receptor (AR) and the estrogen receptor (ER)." (PMID 37370896, 2023). "In particular, we focused on the expression of specific markers of oral cancer, namely the epidermal growth factor receptor (EGFR) and steroid receptors such as the androgen receptor (AR) and the estrogen receptor (ER)." (PMID 37370896, 2023).
penile cancer (3 papers, 2018 to 2022). A primary or metastatic malignant neoplasm that affects the penis. "MicroRNA miR-31-5p regulates the AR gene (Androgen Receptor), which is pointed out as the driver gene in penile cancer." (PMID 35651809, 2022).
pulmonary arterial hypertension (3 papers, 2017 to 2025). Pulmonary arterial hypertension (PAH) is a group of diseases characterized by mean pulmonary artery pressure >20 mmHg and elevated pulmonary arterial resistance leading to right heart failure. "Previous studies have reported that androgens play a critical role in cardiovascular disease and are associated with pulmonary arterial hypertension, and AR had been identified in the right and left ventricles." (PMID 28904974, 2017). "To investigate androgen receptor (AR) expression in pulmonary arterial hypertension (PAH), we established a rat model by administering a single intraperitoneal injection of monocrotaline (MCT)." (PMID 40356960, 2025).
sebaceous carcinoma (3 papers, 2013 to 2022). "Androgen receptor IHC highlights nuclei in sebocytes more diffusely in benign lesions than in poorly differentiated sebaceous carcinomas and sebaceous carcinomas only express EMA in well differentiated cells." (PMID 34287324, 2021). "In vivo androgens can promote growth and development of the human sebaceous gland, while poorly differentiated sebaceous carcinomas have reduced AR expression." (PMID 23403291, 2013). "For sebaceous carcinoma, tumor sequencing revealed RAR-β, androgen receptor, mTOR, and EGFR as the potential investigational approaches." (PMID 35205753, 2022). "Additional immunohistochemical markers, including EMA, adipophilin, and androgen receptor, may be useful in discriminating sebaceous carcinoma from other non-melanoma skin cancers as part of a panel." (PMID 34287324, 2021).
Sertoli Cell-Only Syndrome (3 papers, 2007 to 2024). A type of male infertility in which no germ cells are visible in any of the biopsied SEMINIFEROUS TUBULES (type I) or in which germ cells are present in a minority of tubules (type II). "While the AR protein was expressed, the CDYL protein expression was negligible in the testes of patients with Sertoli cell-only syndrome." (PMID 38786072, 2024). "We examined the expression of AR and CDYL in normal and pathological human testes (Sertoli cell-only syndrome and maturation arrest) by immunochemistry." (PMID 38786072, 2024). "The presence of the androgen receptor in both Leydig and Sertoli cells is not consistent with impaired spermatogenesis leading to a kind of "Sertoli-cell-only" syndrome." (PMID 17408477, 2007).
Spinocerebellar ataxia type 3 (3 papers, 2013 to 2024). "This is the case for spinal and bulbar muscular atrophy (SBMA), which is caused by long poly-Q stretches in the androgen receptor, and spinocerebellar ataxia type 3 (SCA3), which is caused by mutations of the ataxin-3 gene." (PMID 23448461, 2013).
testicular dysgenesis syndrome (3 papers, 2019 to 2025). A syndrome comprising testicular germ cell cancer, cryptorchidism and some cases of hypospadias and male infertility with impaired development of the testis. "The ontological association of androgen receptor coregulation in the H1BH2 arm of the MARS study also suggests that responses to in vivo adult exposures elicits androgen disruption, which has previously been implicated in phthalate-induced testicular dysgenesis syndrome." (PMID 31455814, 2019).
trichoblastoma (3 papers, 2008 to 2026). A benign hair follicle neoplasm with trichoblastic differentiation. "Morpheaform BCC express usually epithelial cell adhesion molecule (EPCAM) (BerEP4), cytokeratin 6 (CK6, that is negative in tricoepithelioma), Ki-67 (negative in trichoepithelioma), and androgen receptor (AR)." (PMID 29261131, 2017). "Androgen receptor is expressed both in BCC and FEP but minimally in trichoblastomas." (PMID 18588684, 2008).
withdrawal syndrome (3 papers, 2008 to 2021). "They suggested that antiandrogen, hydroxyflutamide could initiate the activation via a membrane-initiated, non-androgen receptor-mediated action, providing alternative pathway that might contribute to the withdrawal syndrome." (PMID 18986533, 2008).
acromegaly (2 papers, 2024). Acromegaly is an acquired disorder related to excessive production of growth hormone (GH) and characterized by progressive somatic disfigurement (mainly involving the face and extremities) and systemic manifestations. "Since the disease is associated with polymorphic AR and ERbeta variants that are presumed to be linked to weaker hormone signaling, it may suggest that an incorrect hormonal balance might increase the cardiovascular risk of acromegaly subjects." (PMID 37306894, 2024).
adenosquamous carcinoma (2 papers, 2017 to 2025). A carcinoma composed of malignant glandular cells and malignant squamous cells. "Cells transformed by both AR/AKT/ERG and c‐MYC/sgPTEN generated heterogeneous tumors including adenocarcinoma and adenosquamous carcinoma, consistent with a recent report." (PMID 28297567, 2017). "Adenosquamous carcinoma shows glandular differentiation and a hint of keratinization with strong and diffuse p63 expression, while large cell undifferentiated carcinoma (LCUD) lacks a glandular pattern and is gross cystic disease fluid protein 15 (GCDFP-15) and AR negative." (PMID 40255718, 2025).
age (2 papers, 2019 to 2023). A temporal measurement of the time period elapsed since an identifiable point in the life cycle of an organism. "Finally, we demonstrate that androgens acting via AR protects against age-related degeneration of the adrenal cortex, with implications for our understanding in preventing adrenal degeneration and tumour development." (PMID 31320667, 2019).
alcohol dependence (2 papers, 2011 to 2019). Physical and psychological dependence on alcohol. "This assumption is supported by studies that associate alcohol dependence and its related phenotypes with genes that are involved in sex hormone signaling, biosynthesis, and degradation (estrogen receptor 1, androgen receptor, aromatase, 5α-reductases)." (PMID 31783685, 2019).
alcoholic liver diseases (2 papers, 2018 to 2022). A disorder caused by damage to the liver parenchyma due to alcohol consumption. "In addition, ginseng Huang jiu could improve alcoholic liver disease by regulating the GSTP1, HRAS, AKR1B1, GSTA1, Androgen receptor (AR), GSR, and LDHB genes through bioinformatics analysis." (PMID 36034901, 2022).
allergic asthma (2 papers, 2024). A asthma with a basis in a pathological type I hypersensitivity reaction. "Building on previous research establishing the importance of AR signaling in Th17-mediated inflammation, the authors set out to causally test the role of AR in a widely-used house dust mite (HDM) model of allergic inflammation that mimics human allergic asthma." (PMID 39621312, 2024).
amyotrophy (2 papers, 2022 to 2024). "Dihydrotestosterone (DHT), a male hormone, stimulates AR secretion and has been widely used to treat amyotrophy." (PMID 39239655, 2024).
aortic stenosis (2 papers, 2023 to 2024). Aortic valve stenosis is a aortic valve disease caused by the incomplete opening of the aortic valve. "Their findings showed upregulated AR mRNA levels in patients with aortic stenosis compared to healthy controls." (PMID 39518498, 2024). "Investigating the interplay between androgen levels, AR signaling, and TGF-β expression in human aortic stenosis could provide valuable insights into the sex-based disparities observed in this disease, given that AR has been shown to bind to TGF-β promoter, potentially regulating its expression." (PMID 39518498, 2024).
Arthritis (2 papers, 2016 to 2021). Inflammation of a joint. "Hormone receptors (AR and ESR1) are even more important players in the inflammatory process and can play a potent role in bone inflammatory diseases such as arthritis and bursitis, through the synthesis of steroid hormones (sex hormones and glucocorticoids) via the second messenger cAMP pathway." (PMID 35051095, 2021).
asthenozoospermia (2 papers, 2018 to 2025).
bipolar disorder (2 papers, 2021 to 2022). A disorder of the brain that causes unusual shifts in mood, energy, activity levels and the ability to carry out day-to-day tasks. "Increased levels of AR expression were reported in patients with bipolar disorder." (PMID 35444632, 2022).
brain cancer (2 papers, 2020). A primary or metastatic malignant neoplasm affecting the brain. "However, it was later found that this protein can serve as an oncogenic co-activator of estrogen receptor (ER), androgen receptor (AR) and the STAT3 signaling pathway in breast, prostate, and brain cancers, respectively." (PMID 32660118, 2020).
chronic myelogenous leukemia (2 papers, 2019 to 2022). "Another study revealed that a combination of flutamide and phenprocoumon, which target androgen receptors and vitamin K, respectively, showed synergistic synthetic lethal effects on androgen receptor-positive chronic myeloid leukemia and prostate cancer cells." (PMID 35267623, 2022).
colorectal tumor (2 papers, 2020 to 2021). "Our results of β-AR expression in patients’ tissue samples confirmed that β1 and β2 AR are expressed in colorectal tumour tissues." (PMID 33228233, 2020). "Next, to dissect the mechanism of how AR-modulated circRNA-ARC1 can influence the PCa vs. BCa cell invasion, we focused on miRNAs, since early studies indicated that circRNAs might function as a miRNAs sponge or miRNAs reservoir to alter the breast or colorectal tumor progression." (PMID 34127806, 2021).
cyst (2 papers, 2020 to 2023). A sac-like closed membranous structure that may be empty or contain fluid or amorphous material. "Abundance of mRNA encoding PGRb, AR and STAR was significantly increased in GCs from cysts compared to control GCs, and mRNA levels for both LHCGR and FSHR were significantly lower in cyst CGs in comparison to controls (p < 0.05)." (PMID 37760251, 2023). "Our approach identified a number of potent modulators of cyst growth including two major signalling pathways: androstandione acting via AR-independent signalling and ALK5-mediated signalling." (PMID 31919453, 2020).
dementia (2 papers, 2022 to 2025). Loss of intellectual abilities interfering with an individual's social and occupational functions. "GnRH agonists and androgen receptor inhibitors were both associated with an increased risk of AD (RR, 1.79; 95% CI, 1.14–2.23; and RR, 1.23; 95% CI, 1.13–1.33; p <0.001), non‐AD dementia (RR, 1.57; 95% CI, 1.31–1.86; and RR, 1.25; 95% CI, 1.18–1.33; p <0.001)." (PMID 35293700, 2022). "For AD and non‐AD dementia, GnRH agonists and androgen receptor inhibitors were associated with an increased risk." (PMID 35293700, 2022).
dialysis (2 papers, 2018 to 2024). "Under “Toxicity Functions”, IPA assigned several AR-DEGs to “Inhibition of RXR Function”, fatty acid metabolism, renal failure, and transmembrane potentials." (PMID 30241500, 2018). "AM may be involved in regulating the AR/TGF-β1 signaling pathway and may alleviate peritoneal dialysis-related fibrosis and muscle atrophy in CKD-PF mice." (PMID 39239655, 2024).
endometrioid carcinoma (2 papers, 2020 to 2024). "Clinical data showed that low expression of AR was associated with lower postoperative disease-free survival in patients with uterine endometrioid carcinoma." (PMID 38890503, 2024). "In conclusion, this study showed that DHT suppresses the malignant activity of endometrioid carcinoma via the androgen/AR system." (PMID 38890503, 2024). "Second, although murine experiments suggest that DHT can enhance AR expression in ECC, endometrioid carcinoma associated with a poor prognosis showed a low level of AR expression." (PMID 38890503, 2024). "This study indicates that the androgen/AR system suppresses the malignant activity of endometrioid carcinoma through the downregulation of FOXP4 which will impact new developments in clinical approaches to elderly health." (PMID 38890503, 2024). "We also explored downstream molecules of the androgen/AR pathway and examined the pathological role in the progression of endometrioid carcinoma." (PMID 38890503, 2024). "Meanwhile, a significant association was observed between AR and MMP-9 in endometrioid carcinoma." (PMID 32718331, 2020). "Interestingly, in the analysis by histological subtypes, AR is mainly associated to MMP-2 in HGSC and significantly associated to MMP-9 in endometrioid carcinoma." (PMID 32718331, 2020). "Furthermore, clinical data concerning the expression profiles of FOXP4 and AR in endometrioid carcinoma support our experimental conclusion that the progression of endometrioid carcinoma can be controlled by stimulating an androgen/AR system and/or suppressing its downstream molecular target, FOXP4." (PMID 38890503, 2024).